IDH1 (isocitrate dehydrogenase (NADP(+)) 1)
Diseases named in the same sentence as IDH1 in open-access papers (continued):
Sharing a sentence is not in itself a finding about the gene and the disease.
glioma (continued). "Clinical trials phases I/II are currently on going for IDH1-positive grade II gliomas (NCT02193347) and for high grade gliomas (NCT02454634) and therapeutic results will be soon calculated." (PMID 35628161, 2022). "The RT-qPCR assay showed that the six signature genes (TRIM24, IDH1, LBR, HMG20B, USP49, and RCC1) were up-regulated in glioma cell lines in mRNA expression level." (PMID 36246611, 2022). "In gliomas, the hypoxia-inducible factor 1-alpha (HIF-1a) is a significant pro-angiogenic and pro-glycolysis transcription factor that is increased in IDH1 mutant GB cells." (PMID 35806212, 2022). "Phase I studies (NCT02746081 and NCT03127735) of BAY‐1436032 for IDH1‐mutant solid tumors and AML demonstrated it was well tolerated and showed durable ORR in lower grade glioma." (PMID 36254250, 2022). "IDH1/2 mutations are ideal tumor-specific antigens because they occur at specific codons in IDH1 and IDH2 and are commonly found in glioma cells." (PMID 34603319, 2021). "In both WHO all-grade gliomas and within the same WHO grade gliomas, the level of HOXB7 mRNA was more highly expressed in IDH1 wild type gliomas than in IDH1 mutant types (p < 0.0001)." (PMID 34458259, 2021). "In one study comparing the abundance of NAAAs in individuals with mutIDH1R132H and WT IDH1 glioma, MRS revealed that total NAAAs were slightly higher in mutIDH1R132H than WT IDH1 gliomas." (PMID 35028610, 2021). "In cell viability dose–response assays, IDH1mut glioma cells were much more sensitive to an FDA-approved pan-HDACi, panobinostat, compared to their IDH1/2wt counterparts, with a 4.1 fold difference in IC50 values." (PMID 34424450, 2021). "Subsequently, the radiomics signatures were utilized to predict the genetic profile of ATRX, IDH1/2, MGMT and 1p19q co-deletion, as well as differentiating low-grade glioma from high-grade glioma." (PMID 34944806, 2021). "IDH1 and IDH2 are promising molecular targets for precision therapy not only in gliomas but also in other malignancies." (PMID 35996504, 2021). "There is one more IDH1 peptide vaccine, PEPIDH1M, for recurrent grade II gliomas (RESIST) the safety of which is now being tested in combination with the standard chemotherapy, temozolomide (NCT02193347)." (PMID 34356864, 2021). "Our results showed that constructed multiparametric model from MRI radiomics features can identify IDH1, ATRX, MGMT, and EGFR in preoperative MRI scans of patients with glioma." (PMID 34056604, 2021).
glioma (continued). "Since IDH1/2mut occurs early in gliomagenesis, and the histone/DNA hypermethylation state of IDH1/2mut gliomas is largely retained even during disease progression, there is a possibility that epigenetic modifiers may be particularly effective against IDH1/2mut glioma." (PMID 34424450, 2021). "We noted that in lower grade glioma patients, the survival time with high expression of HOXB7 subgroup was similar to that of the IDH1 wild type subgroup." (PMID 34458259, 2021). "Furthermore, IDH1 mutation status, which is an important molecular classifier of low grade gliomas and secondary GBM63, was not available in either study to examine whether associations vary according to IDH1 status." (PMID 33953301, 2021). "For example, while IDH1/2 mutations are known to be associated with young adult gliomas, our paired mutation-subtype analysis provides improved resolution, showing IDHmut-non-codel glioma enrichment in young adults whereas IDHmut-codel gliomas are enriched in later-onset cases." (PMID 34788626, 2021). "Then, we explored the B2M expression in gliomas with respect to World Health Organization (WHO) grade, IDH1 status, and different molecular subtypes." (PMID 33960680, 2021). "Specifically, IDH1 and IDH2 are wild‐type (IDHwt) in the most aggressive glioma types, which include about 95% of GBM, whereas they are mutated (IDHmut) in gliomas with better prognosis." (PMID 33720519, 2021). "Except Ki67, GFAP and S100, other glioma biomarkers, such as ATRX, IDH1 and 1p/19q statues can also be identified by medical imaging." (PMID 34831392, 2021). "In the same WHO grade glioma, the HOXB7 protein was expressed more highly in IDH1 wild type than that in IDH1 mutant type." (PMID 34458259, 2021). "Therefore, IDH1 and IDH2 mutations may be involved in the tumorigenesis of gliomas." (PMID 34961815, 2021). "wt-IDH1 gliomas, WHO grade IV, high grade gliomas (HGG), present with several genomic alterations and higher somatic mutation frequency versus low grade gliomas (LGG)." (PMID 34422657, 2021). "Two IDH inhibitors, ivosedinib (an IDH1 inhibitor) and enasedinib (an IDH2 inhibitor) demonstrated efficacy against gliomas, cholangiocarcinomas, and AML in clinical trials." (PMID 34831002, 2021). "Further analysis identified that the expression of METTL7B was higher in glioma with a higher WHO grade and the METTL7B level in IDH1 wild-type was higher than that of mutant type." (PMID 33996568, 2021). "High HOXB7 expression is significantly positively correlated with GBM and IDH1 wild type status, which indicates that HOXB7 functions as an oncogene in gliomas." (PMID 34458259, 2021). "In our own cohort, 9/100 gliomas were hypermutated, all 9 had been previously treated with TMZ, all 9 had MGMT promoter methylation, and 5/9 were IDH1 mutant." (PMID 32051040, 2020). "In all gliomas, the median MET T/N ratios in IDH1-mutant and IDH1-wildtype tumours were 3.6 (IQR 2.84–5.59) and 5.91 (4.57–7.35), respectively." (PMID 32382870, 2020). "The IDH1 inhibitor vorasidenib is currently being tested in a phase III study of recurrent, low-grade glioma (NCT04164901)." (PMID 33396284, 2020). "All 9 hypermutated gliomas had MGMT promoter methylation and were post-TMZ, and 5/9 (56%) were IDH1 mutant." (PMID 32051040, 2020). "The inhibitor of mutant IDH1 ivosidenib and mutant IDH2 enasidenib exhibited positive responses in patients with relapsed or refractory gliomas, intrahepatic cholangiocarcinomas, and chondrosarcomas in phase I/II clinical trials." (PMID 31847543, 2020). "Hereafter, 30 mice were implanted with three glioma cell lines (LNT-229, LNT-229 IDH1-R132H, GL261)." (PMID 33138036, 2020). "Genetic alterations in IDH1 or IDH2, TERT, and co-deletion of chromosome arms 1p and 19q (1p/19q codel) were rather found in low grade gliomas (LGG; grades II-III)." (PMID 33154756, 2020).
glioma (continued). "To explore the correlation between FTL and glioma aggressiveness, we compared FTL expression in different IDH1/2 status." (PMID 32677981, 2020). "They cautioned that MET uptake for glioma grading according to the 2016 WHO classification was more consistent and accurate for IDH1-wildtype tumours than for IDH1-mutant tumours." (PMID 32382870, 2020). "Moreover, based on DZIP3 expression, we could reclassify the IDH1 wild-type lower-grade glioma." (PMID 33229627, 2020). "We further observed that five lncRNAs interact and are closely related to the clinical symptoms of glioma patients (WHO grade, IDH1 status, 1q19q status, and MGMT)." (PMID 33391355, 2020). "The results revealed that the risk score has a significant correlation with the clinical features of glioma, including TCGA transcriptome subtypes, WHO grade, IDH1 status, 1p/19q status, and MGMT promoter methylation status." (PMID 33230136, 2020). "FTO plays carcinogenic roles through maintaining the stability of gliomas, especially the stability of oncogene homologues (c-Myc) and CCAAT-enhancer-binding protein-α (CEBPA) transcripts in IDH1/2 mutant gliomas." (PMID 32943100, 2020). "Novel biomarkers such as isocitrate dehydrogenase 1 gene (IDH1) and O6-methylguanine-DNA-methyltransferase (MGMT) gene methylation status have been proposed as useful tool to predict prognosis and survival of glioma patients." (PMID 33282092, 2020). "In glioma patients, selective oral IDH inhibitors of IDH1 (i.e., ivosidenib, BAY-1436032), pan-IDH1/2 (i.e., AG-881), and vaccination strategies targeting the IDH1R132H mutation are currently under clinical evaluation." (PMID 32213992, 2020). "Then, Cox regression analysis verified the independence of the clinical prognostic significance of DZIP3 in glioma after adjusting age at diagnosis and WHO grade and IDH1 status in both all grade and lower grade glioma in CGGA RNA-seq cohort." (PMID 33229627, 2020). "In 2016 WHO classification, mutations in the epigenetic modulator genes isocitrate dehydrogenase 1 or 2 (IDH1 or IDH2) and codeletion of chromosomal arms 1p/19q (1p/19q codel) have become key biomarkers for glioma classification." (PMID 32373523, 2020). "Screening for hypermutation-associated MMR defects therefore appears to be of greatest value in recurrent, post-TMZ gliomas, especially MGMT-methylated and/or IDH1 mutant tumors." (PMID 32051040, 2020). "FLT-PET/CT was able to distinguish the IDH1-mutant tumours from wildtype tumours not only in all gliomas but also in grade II and III gliomas." (PMID 32382870, 2020). "Currently, D-2-HG is being used as a biomarker to monitor the disease progression, and mutants IDH1/IDH2-specific inhibitors are in clinical trials for AML and glioma." (PMID 31900386, 2020). "IDH1 and IDH2 exhibit high sequence similarity and are often present in various malignancies, including glioma, leukemia, and cartilaginous tumors." (PMID 33014795, 2020). "In actual clinical practice, a glioma should be classified as wildtype when both R132H-IDH immunohistochemistry and subsequent IDH1/2 sequencing revel wildtype sequences at IDH1 codon 132 and IDH2 codon 1721." (PMID 32382048, 2020).
glioma (continued). "In addition, the high baseline level of sPD-L1, decreased level of sPD-L1 after RT and some other clinical factors, such as IDH-1 WT tumors, GBMs, tumors located in the brainstem and tumors with a Ki-67 expression rate > 27.5%, were demonstrated to be related to poor prognosis in glioma patients." (PMID 33224142, 2020). "The aim of this study was to investigate the interplay among IDH1, TL, ATRX and TERT/ALT using a newly developed distinctive methodology that allowed determination of glioma cell-specific telomere length (CS-TL) on a single cell level." (PMID 31960234, 2020). "When analysing the uptake values in 36 grade II and III gliomas separately, the median MET T/N ratios in IDH1-mutant and IDH1-wildtype tumours were 3.59 (IQR 2.87–5.28) and 5.14 (3.97–6.06), respectively." (PMID 32382870, 2020). "In this study, 47.6% of glioma patients were detected ctDNA including 1p/19q, MDM2, ERBB2, IDH1, CDKN2A, CDK4, PDGFRA, CCNE1, MET." (PMID 32973641, 2020). "However, these therapies could have long-term negative effects, given the relationship between IDH1/2 mutations and the less aggressive behavior of gliomas." (PMID 32570988, 2020). "On the basis of clinical risk factors, we created a new classification and divided lower grade gliomas into IDH1-WT, IDH1-MUT and ACAA2 high, and IDH1-MUT and ACAA2 low types." (PMID 32280672, 2020). "For instance, IDH1 silencing specifically increases erlotinib (an EGFR, epidermal growth factor receptor, inhibitor) efficacy in patient-derived glioma-initiating cells (GICs) carrying EGFR amplification." (PMID 31010244, 2019). "Of note, several drugs directed against epigenetic pathways (e.g., HDACs, mutant IDH1, EZH2, and DNMT) have been clinically tested for different malignancies, including glioma." (PMID 30644073, 2019). "We analyzed the role of the glioma ITSS grade in predicting pathological grade and the expression status of IDH1, MGMT, and 1p19q." (PMID 31745161, 2019). "IDH1-mutant glioma required NAMPT for the production of NAD+ and showed vulnerability to the inhibition of NAMPT, because mutant IDH1 reduces the expression of NAPRTase22." (PMID 31123329, 2019). "A two-sample t-test was used for metabolite comparisons between IDH1 (n = 15) and IDH2 (n = 5) mutant gliomas." (PMID 30791611, 2019). "Previous studies have mentioned that the patterns of IDH1/2 and TERT were involved in glioma classification." (PMID 31690770, 2019). "Two clinical trials are actively recruiting grade II glioma (NCT02193347) and grade III/IV glioblastoma (NCT02454634) patients, assessing safety and tolerability of anti-IDH1(R132H) peptide vaccine." (PMID 30708988, 2019). "Here, we used surgical specimens of low-grade glioma (WHO grade II astrocytoma and oligodendroglioma) with mutant IDH1/2 and showed a co-staining of the tumor cells with anti-IDH1 and anti-CRMP5 antibodies." (PMID 31861603, 2019). "Mutant IDH1 cooperated with PDGFA and inactivation of CDKN2A, ATRX, and PTEN to promote glioma development." (PMID 31450721, 2019). "IDH1 is reported to be the main generator of NADPH in the brain and in gliomas, producing up to 60% of the cell’s NADPH." (PMID 31888244, 2019). "Similar to human IDH1-mut gliomas, reductions in CD45+ cells, including microglia, macrophages, monocytes, and polymorphonuclear leukocytes, were reported in the IDH1-mut murine tumors." (PMID 30857299, 2019). "Thus, we considered that IDH1-mutant cell lines, which usually grow much faster than the original tumor in the brain, may lose methylation preferentially in late-replicating regions and show a similar methylation profile as recurrent glioma samples." (PMID 30760837, 2019). "A fraction of IDH1-mut glioma patients have isoform-specific antibodies and displayed an IFN-γ T-cell response against a mutant IDH1 (mutIDH1) protein." (PMID 30857299, 2019).
glioma (continued). "Evidently, the overall survival of glioma patients can be affected by many important clinical and genetic factors, such as age, tumor grades, ATRX status, IDH1/2 status, telomerase reverse transcriptase (TERT) status, and so on16,17." (PMID 30936423, 2019). "In line with this, a recent study showed that CRISPR/Cas9-mediated knockout of IDH1 R132H induces genome-wide DNA demethylation and closely recapitulates G-CIMP-low phenotype in isogenic glioma cell lines." (PMID 31652645, 2019). "However, most studies in this analysis did not take into account confounding factors such as IDH1/2 mutational status, and a subgroup analysis of types of gliomas showed that impact of loss of 9p on overall survival was particularly present in the glioblastoma subtype." (PMID 29663171, 2018). "The notion that inactivation of tumor-suppressor gene(s) permits IDH1R132H existence and expression in glioma may account for the continuous presence of IDH1R132H in recurrent gliomas, even though some recurrent gliomas underwent genetic deletion of mutant IDH1 allele and copy number alterations." (PMID 30416682, 2018). "Furthermore, the same data imply that the IDH1 mutation may in fact be a very early mutative event in gliomagenesis, as another frequent glioma mutation 1p/19q codeletion is not acquired before mIDH1 if they are to copresent." (PMID 29303363, 2018). "In this study, we performed mRNA and proteomic profiling of IDH1/2 WT versus IDH1/2 mutant Grade II and III gliomas in order to better understand gene expression differences contributing to worse overall survival in IDH1/2 WT gliomas." (PMID 30647847, 2018). "Among the 175 significantly differentially expressed genes, we identified TAGLN2 as an upregulated gene in IDH1/2 WT grade II and III gliomas compared to IDH1/2 mutant tumors (p-value=7.73×10−5; FDR=0.053) in our institutional cohort." (PMID 30647847, 2018). "Interestingly, BRAF V600E never occurs alongside IDH1/2 mutations and may also define a subgroup of slowly progressing gliomas with better treatment response." (PMID 30510501, 2018). "In addition, TET2 promoter methylation, but not TET2 mutations, may represent an alternative mechanism of pathogenesis in low-grade gliomas lacking IDH1/2 mutations." (PMID 29849955, 2018). "We further employed the MR-UM approach to investigate intraoperatively obtained resection material from two glioma patients, one with a glioblastoma (WHO grade IV, IDH1 wildtype) and one with an oligodendroglioma (WHO grade II, IDH1 mutant)." (PMID 30686972, 2018). "In gliomas, cytosolic NADP+-dependent isocitrate dehydrogenase 1 (IDH1) became a more valuable determinant of disease characteristics, sensitivity to chemo/radiation therapy, and OS in glioma patients when compared with histological grades." (PMID 29643764, 2018). "Homologous mutations in the metabolic enzymes isocitrate dehydrogenase 1 and 2 (IDH1 and IDH2) are found in acute myelogenous leukemia, colon cancer and glioma." (PMID 29692895, 2018). "Another study provided evidence that the PARP1-associated DNA reparation pathway was compromised in IDH-mutant gliomas due to decreased NAD+ content; importantly, targeting the PARP1 DNA repair pathway markedly sensitized IDH1-mutant gliomas to temozolomide." (PMID 30279357, 2018). "Mutations in genes involved in important metabolic pathways, such as isocitrate dehydrogenase 1 and 2 (IDH1/IDH2), are important cancer drivers (e.g., gliomas and leukemias)." (PMID 30170631, 2018).